KIAA1217 (KIAA1217)
Description:
Required for normal development of intervertebral disks.
Synonyms: SKT; DKFZP761L0424; ETL4
Tractability: PROTAC: ubiquitination databases record sites on it; its protein half-life has been measured.
Gene: Protein-coding gene on chromosome 10 (23,694,746 to 24,547,848, forward strand). Ensembl gene ENSG00000120549.
Subcellular location: Cytoplasm, cytoskeleton, microtubule organizing center, centrosome; Cytoplasm
Subcellular location (Human Protein Atlas): Cytosol; Nucleoplasm
Gene Ontology:
Biological process: embryonic skeletal system development
Cellular component: centrosome; cytoplasm
Genetic constraint (gnomAD): Loss-of-function variants: 82 observed, 158.95 expected, observed/expected ratio (o/e) 0.52, 90% interval 0.43 to 0.62. The upper end of that interval is the gene's LOEUF score, 0.62, which puts it in group 2 of 6, group 1 being the genes least tolerant of losing a copy. Missense variants: 2,315 observed, 2,529.9 expected, observed/expected ratio (o/e) 0.92, 90% interval 0.88 to 0.95. Synonymous variants: 886 observed, 946.88 expected, observed/expected ratio (o/e) 0.94, 90% interval 0.88 to 0.99.
Homologues: Orthologues: chimpanzee KIAA1217 (99% identical), macaque KIAA1217 (96% identical), dog KIAA1217 (84% identical), pig KIAA1217 (83% identical), mouse Etl4 (81% identical), rat Etl4 (80% identical), rabbit KIAA1217 (59% identical), guinea pig KIAA1217 (53% identical), tropical clawed frog KIAA1217 (50% identical), zebrafish si:ch211-207d6.2 (28% identical), Drosophila melanogaster CG32809 (16% identical), Caenorhabditis elegans gldi-9 (10% identical). Paralogues in human: SRCIN1 (23% identical).
Diseases named in the same sentence as KIAA1217 in open-access papers:
KIAA1217 is named in the same sentence as 24 diseases in open-access papers, as found by Europe PMC text mining. Sharing a sentence is not in itself a finding about the gene and the disease. The quoted sentences say what the papers report.
lumbar disc herniation (3 papers, 2016 to 2021). "The human SKT gene (KIAA1217) was believed to be a good candidate for a lumbar disc herniation (LDH) susceptibility because SKT is expressed in NP of IVDs." (PMID 30464887, 2018).
non-small cell lung carcinoma (3 papers, 2016 to 2023). A group of at least three distinct histological types of lung cancer, including non-small cell squamous cell carcinoma, adenocarcinoma, and large cell carcinoma. "KIAA1217-RET, resulting from the rearrangement of chromosome 10, was generated by the fusion of KIAA1217 exon 11 and RET exon 11 from a non-small cell lung cancer patient." (PMID 27150058, 2016). "KIAA1217 shows different splicing in esophageal squamous cell carcinoma and intron retention of KIAA1217 has been found in non-small cell lung cancer, but it is not supported by results of RT-PCR." (PMID 36950012, 2023). "Intron retention of KIAA1217 has been found in non-small cell lung cancer, but RT-PCR results do not support this result." (PMID 33563334, 2021).
breast carcinoma (2 papers, 2013 to 2021). "Deletion, amplification and interchromosomal translocation of KIAA1217 were previously discovered in two breast cancers." (PMID 23496902, 2013). "Copy number variation of KIAA1217 is also frequently observed in HCC or breast cancer." (PMID 35008530, 2021).
colon cancer (2 papers, 2021 to 2024). "Mutations in KIAA1217, POLD1, PIEZO1, NBEAL2, DDX17, and PARP14 were significantly more prevalent in patients with colon cancer and PRShigh than in those with PRSlow." (PMID 38577604, 2024).
hepatocellular carcinoma (2 papers, 2021 to 2024). A malignant tumor that arises from hepatocytes. "KIAA1217 has not to our knowledge been described in the retina; however, it has been reported to play a crucial role in hepatocellular carcinoma, promoting cell migration and invasion." (PMID 38994994, 2024).
lung adenocarcinoma (2 papers, 2016 to 2021). A carcinoma that arises from the lung and is characterized by the presence of malignant glandular epithelial cells. "In particular, a novel KIAA1217-RET fusion gene was identified in lung adenocarcinomas." (PMID 35008530, 2021). "In addition, a novel KIAA1217-RET fusion gene was identified in lung adenocarcinomas and revealed that the KIAA1217-RET fusion gene functions as an oncogenic driver gene." (PMID 35008530, 2021). "Previously, we screened for ALK, ROS1, and RET fusion genes in 795 lung adenocarcinoma specimens and identified the novel KIAA1217-RET fusion gene containing KIAA1217 exon 11 and RET exon 11 from a patient with a 4-cm tumor mass (red arrow)." (PMID 27150058, 2016).
lung carcinoma (2 papers, 2016 to 2024). "KIAA1217 is a novel RET partner gene in lung cancer and contains two CCDs that could promote ligand-independent dimerization in the RET fusion protein." (PMID 27150058, 2016). "According to previous studies, KIAA1217 is a fusion partner of rearranged during transfection (RET) fusion gene, and its fusion to RET leads to oncogenic transformation in lung cancer." (PMID 38741142, 2024).
pancreatic cancer (2 papers, 2021 to 2024). "Based on genetic association studies in pancreatic cancer databases, KIAA1217 is upregulated, suggesting that KIAA1217 may be a putative target for pancreatic cancer." (PMID 35008530, 2021). "KIAA1217, SLC44A1, INPP5B, and SDK1 were reversely correlated with some miRNAs not affecting patient survival, which shows these are potential therapeutic targets for pancreatic cancer." (PMID 38741142, 2024).
adenoma (1 paper, 2020). A neoplasm arising from the epithelium. "For module yellow, which is progressively up-regulated from normal stroma to adenoma to mCA, the top candidate hub genes consisted of CDH1, ST14, EHF, KRT8, and KIAA1217, all of which have important roles in epithelial cells, and/or are associated with tumour malignancy." (PMID 32218455, 2020).
Cirrhosis (1 paper, 2021). A chronic disorder of the liver in which liver tissue becomes scarred and is partially replaced by regenerative nodules and fibrotic tissue resulting in loss of liver function. "Moreover, further studies are needed to determine whether KIAA1217 represents a potential biomarker for the prediction of disease progression or a therapeutic target in cirrhosis in the future." (PMID 35008530, 2021).
liver cirrhosis (1 paper, 2021). "Notably, the high expression level of KIAA1217 in patients with liver cirrhosis (83.33%) was significantly higher than that in HCC tissues (47.06%)." (PMID 35008530, 2021). "Since we documented that KIAA1217 induced EMT in HCC cells and was highly expressed in cirrhotic liver tissues, we speculate that KIAA1217 may play a certain role in the progression of liver fibrosis and liver cirrhosis, which requires further investigation." (PMID 35008530, 2021). "As liver cirrhosis is closely related to the development of HCC, we considered that the presence of cirrhotic liver tissues interferes with our judgment of the expression of KIAA1217 in HCC tissues compared with adjacent nontumor tissues." (PMID 35008530, 2021).
ovarian carcinoma (1 paper, 2021). A malignant neoplasm originating from the surface ovarian epithelium. "Interestingly, another study by our team also observed a truncated transcript of KIAA1217 expressed in ovarian cancer cell lines (unpublished data)." (PMID 35008530, 2021).
cancer (8 papers, 2010 to 2025). A tumor composed of atypical neoplastic, often pleomorphic cells that invade other tissues. "To date, few reports have investigated KIAA1217, of which only a few studies have described its relation to the development of cancer." (PMID 35008530, 2021). "STAT3 overexpression substantially increased the migration and invasion of HepG2 cells with KIAA1217 silencing, as evidenced by the wound-healing assay, transwell migration assay, and cancer cell spheroid invasion assay in a 3D setting." (PMID 35008530, 2021). "Here, we found a novel RET fusion gene, KIAA1217-RET, and examined the functional differences of RET51 and RET9 protein, fused with KIAA1217 in cancer progression and drug response." (PMID 27150058, 2016). "Therefore, KIAA1217, an oncogene, also appears to participate in the occurrence and development of cancer in the form of fusion genes via genome rearrangements." (PMID 35008530, 2021). "However, the potential role and mechanism of KIAA1217 in the progression of cancer remains unclear." (PMID 35008530, 2021). "In addition, long-term survivors also have antibodies against proteins known to promote cancer growth, such as PIEZO1, aggressiveness such as TMPRSS2, and Epithelial Mesenchymal Transition such as KIAA1217 or C11orf45, which are biomarkers related to immune checkpoint proteins." (PMID 40887652, 2025). "In addition, in contrast to the matched nontumor tissues, KIAA1217 expression was increased in the 18 other types of cancers, which was analyzed using the GEPIA web server." (PMID 35008530, 2021).
tumor (7 papers, 2016 to 2024). "Neither KIT nor PDGFRA mutations were detected by Sanger sequencing; however, next-generation sequencing (NGS) identified an FGFR2-KIAA1217 gene fusion in the tumor tissue." (PMID 35978808, 2022). "EMT plays a critical role in tumor invasion and metastasis, and thus we assessed the effect of KIAA1217 on EMT by analyzing the expression of EMT markers and EMT-related transcription factors." (PMID 35008530, 2021). "Consequently, KIAA1217-RET fusion led to the increase in tumor cell invasion." (PMID 27150058, 2016). "Six overlapping AS events regulated by SF3B4 in tumor samples were finally verified, including 1 SE event (ATP2B4) and 5 RI events in 4 genes (SRSF5, PHF6, SNHG12, KIAA1217)." (PMID 33563334, 2021). "In the five iCCA patients with FGFR2 fusions (BICC1 (n=2), KIAA1217, TACC1, CCDC6), two confirmed PRs and a SD (25% tumour reduction) of 24–41 weeks duration were observed." (PMID 28972963, 2017). "To validate tumorigenic potential of a KIAA1217-RET fusion, we tested cell growth and tumor-forming ability in vitro." (PMID 27150058, 2016).
KIAA1217 also shares sentences with these, for which no sentence is quoted: Alzheimer disease (1 paper); cholangiocarcinoma (1); dementia (1); esophageal squamous cell carcinoma (1); Huntington disease (1); liver fibrosis (1); neurodegenerative disease (1); Parkinson disease (1); prostate carcinoma (1); thyroid cancer (1).